HK3 (hexokinase 3)
Diseases named in the same sentence as HK3 in open-access papers (continued):
Sharing a sentence is not in itself a finding about the gene and the disease.
tumor (44 papers, 2003 to 2025). "In ESCC, creatine accumulation combined with loss of hexokinase 3 (HK3) synergistically promotes M2 polarization of tumor-associated macrophages, contributing to the establishment of an immunosuppressive microenvironment." (PMID 41050070, 2025). "We analyzed the HK3 expression level in samples from TCGA stratified according to tumor grade, IDH mutation status and MGMT promoter methylation status." (PMID 37779195, 2023). "HK3 deficiency induced significant reduction in mouse tumor weight and volume relative to the control group." (PMID 37106446, 2023). "For further analysis of the function of HK3 in anti‐tumor immune response, seven associated immune metagenes were evaluated." (PMID 32508023, 2020). "Cluster 1 contained genes significantly upregulated in AMPKα1/α2–deficient tumor-infiltrating Treg cells and included genes encoding chemokines (Ccl2, Ccl7, Ccl8), modulators of lipid metabolism (Cd36, Pparg, Lpl, Abca1), and glycolytic enzymes (Hk2, Hk3)." (PMID 40100289, 2025). "Furthermore, the modification of HK3 can alter tumour cell behaviour in M2 tumour‐associated macrophages." (PMID 41190507, 2025). "The impact of HK3 deficiency on RCC tumorigenesis was evaluated using tumor-bearing mouse models." (PMID 37106446, 2023). "Additionally, the Ki67 protein in mouse tumor tissues was revealed to be reduced by HK3 deficiency, suggesting that HK3 knockdown suppressed RCC tumorigenesis in vivo." (PMID 37106446, 2023). "Additionally, the circZBTB44 deficiency induced decrease in xenograft tumor weight, volume and growth rate was significantly reversed by HK3 overexpression." (PMID 37106446, 2023). "The combined increased abundances observed in the proteins encoded by Cav1, Pld3 and Hk3 also highlight the interplay with tumor cell metabolism modifications, leading to the suppression of cancer cell stemness and the deleterious effects of cancer-associated fibroblasts." (PMID 36430209, 2022). "Similarly, transcription of gene encoding hexokinase 3 (Hk3) was upregulated in tumor obtained from WT mice in comparison to ChREBP-KO tumor by a fold of 1.5." (PMID 34685767, 2021). "Therefore, it was found that HK3 is also implicated in the impact of macrophages on tumor cells." (PMID 38714539, 2024). "These ER+ tumours also demonstrate metabolic optimization through regulators such as HK3, LDHAL6A, ADH6, and PRKCB, which collectively shift metabolism toward greater efficiency." (PMID 41007296, 2025). "The results corroborated the database predictions, demonstrating that the mRNA and protein expression levels of HK3 were notably elevated in tumor tissues compared to adjacent normal tissues." (PMID 39179546, 2024). "This indicates that at the level of NB cells, HK3 can regulate the biological behavior of the tumor." (PMID 38714539, 2024). "We observed that the decreased expression of HK3 in M2 macrophages indirectly led to a reduction in the proliferation, invasion, and migration abilities of NB tumor cells." (PMID 38714539, 2024). "HK3 expression is significantly increased in ccRCC tissues, predicting tumor progression and poor prognosis." (PMID 39014460, 2024). "Simultaneously, tumor cells with HK3 knockdown, co-cultured with macrophages, showed significantly lower increases in tumor size and weight compared to the control group." (PMID 38714539, 2024). "Continuing our investigations in vivo, consistent with the in vitro effects, we observed a reduction in tumor volume and weight after HK3 knockdown or treatment with Corosolic acid." (PMID 39179546, 2024). "Our previous results have confirmed that HK3 plays a role in regulating PD-L1, thereby contributing to immune evasion in tumor cells." (PMID 39179546, 2024). "Our study elucidates that HK3-mediated O-GlcNAcylation of EP300 is involved in tumor immune evasion." (PMID 39179546, 2024).
tumor (continued). "Data from a comprehensive analysis of the TCGA and CPTAC databases revealed that in ccRCC patients, HK3 expression in primary tumor tissues was markedly elevated compared to normal tissues, at both mRNA and protein levels." (PMID 39179546, 2024). "We have further analyzed the pathways involved using KEGG and GSEA, and it appears that HK3 is not only involved in specific immunity but also mediates innate immunity within the tumor microenvironment." (PMID 39179546, 2024). "Specifically, HK3 in M2-TAMs was discovered to play a role in the macrophage-mediated effects on tumor cells." (PMID 38714539, 2024). "Previous research has shown that macrophages co-cultured with tumor cells displaying M2-like phenotypes exhibited HK3 overexpression." (PMID 38714539, 2024). "Ki67 protein expression was reduced in tumor tissues of mice in the circZBTB44 knockdown groups, and was elevated by HK3 overexpression compared with the sh-circ + oe-NC groups." (PMID 37106446, 2023). "Promoter methylation in the SLC40A1 gene has been reported to affect differential expression, and the expression of HK3 has been shown to be upregulated in CpG island methylator phenotype-high tumours, supporting our findings." (PMID 37884919, 2023). "In the datasets from CGGA, HK3 expression was still a better predictor of OS, which was consistent the results of tumor grade and age." (PMID 37779195, 2023). "It facilitates RCC cell proliferation and migration in vitro and promotes tumor growth in vivo by up-regulating HK3." (PMID 37106446, 2023). "Subsequently, we also compared the specificity and sensitivity of HK3 expression, patient age at diagnosis, and tumor grade in predicting OS." (PMID 37779195, 2023). "qRT-PCR and western blot analyses showed that HK3 expression was evidently down-regulated in mouse tumor tissues of the sh-HK3 group." (PMID 37106446, 2023). "PPT1 and HK3 were overexpressed in tumor and its high expression was correlated with poor prognosis, while high ADCK3 expression was correlated with better survival." (PMID 37434985, 2023). "HK3 is reported to be highly expressed in tumor tissues of clear cell RCC patients and is indicated to activate apoptosis and epithelial-mesenchymal transition." (PMID 37106446, 2023). "In order to further verify the ability of HK3 as a tumor marker of ccRCC, we collected clinicopathological characteristics baseline in relation to HK3 mRNA expression status in 910 ccRCC patients from TCGA and FUSCC cohorts." (PMID 34239350, 2021). "Cancer-promoting HK3 signal mediates the infiltration of monocytes/macrophages and promotes tumor immune escape." (PMID 34239350, 2021). "It shows that HK3 serves as a promising and potential tumor marker predicting prognosis and survival of ccRCC patients." (PMID 34239350, 2021). "PPI showed that HK2 was closely related to HK1, GPI, and HK3, all of which played an important role in tumor proliferation." (PMID 34708035, 2021). "We grouped all patients according to their gender, stage, mutation burden, immune-cells enriched, and found that patients with high HK3 had a significant decrease in survival rate, increased tumor stage, and increased immune cell infiltration (p<0.01)." (PMID 34239350, 2021). "In order to reduce the heterogeneity of tumor tissues, and to further confirm localization of HK3 in immune cells, we included and analyzed three single-cell RNA-seq (scRNA-seq) datasets, GSE11136, GSE13955 and GSE145281." (PMID 34239350, 2021). "As the rate‐limiting enzyme for glycolysis, HK3 is dysregulated in various tumors and participates in tumor progression." (PMID 32508023, 2020). "In this study we build on our prior work to show that HK2, but not the other brain-specific isoforms of hexokinase, HK1 and HK3, drives tumor metabolism in GBM." (PMID 27588472, 2016).
tumor (continued). "HK3, in turn, impairs TAM cross-presentation capacity by promoting TFEB nuclear translocation and excessive lysosomal activation and antigen degradation, thereby undermining anti-tumor immunity; targeting HK3 restores antigen presentation and synergizes with immune checkpoint blockade." (PMID 41459510, 2025). "Studies show that HK3 often collaborates with immune cells to promote tumor progression." (PMID 38714539, 2024). "In our previous study, it was demonstrated that the polarization of M2 macrophages in the tumor microenvironment could be regulated by tumoral HK3 both in vitro and in vivo." (PMID 38714539, 2024). "Confirmed that HK3 is involved in the interaction between tumor cells and M2 macrophages." (PMID 39179546, 2024). "Under these conditions, HK3 also appears to exert an inhibitory effect on tumor growth." (PMID 38714539, 2024). "Notably, shHK3 suppressed both basal levels and UDP-GlcNAc-elevated PD-L1 and O-GlcNAcylation, demonstrating that the elevated basal level of tumor HK3, in addition to UDP-GlcNAc-induced HK3, both contributed to PD-L1 expression upon UDP-GlcNAc stimulation." (PMID 39179546, 2024). "Furthermore, shHK3 suppressed both basal levels and OGT-elevated PD-L1 and O-GlcNAcylation, signifying that the high basal level of tumor HK3, along with OGT-induced HK3, both played a role in PD-L1 expression following OGT stimulation." (PMID 39179546, 2024). "Collectively, these findings support our hypothesis that HK3 can drive tumor cells toward a more M2 macrophage and enhance the antitumor activity of anti-PD-1 treatment through remodeling of the TME." (PMID 39179546, 2024). "In our experiment, we hypothesized that tumor cells with knocked-down HK3 could reduce M2-like macrophage characteristics, possibly through intermediary-secreted mediators." (PMID 38714539, 2024). "The experiments in vitro and in vivo both illuminated the tumor-promoting role of HK3." (PMID 38714539, 2024). "Also, in numerous studies, HK3 has been identified as a potential marker for regulating the tumor metabolic microenvironment and malignant progression, with predictive efficacy for tumor progression and prognosis." (PMID 37434985, 2023). "Interestingly, the rate-limiting enzyme-coding genes in the glycolysis pathway showed inconsistent expression pattern in tumor cells compared with normal: HK3 and PFKP were overexpressed, while PFKM was downregulated." (PMID 37553601, 2023). "The AUCs based on HK3 expression for one-, three-, and five-year OS were 0.814, 0.772, and 0.712, respectively, in TCGA datasets and were similar to the corresponding AUCs based on age and tumor grade." (PMID 37779195, 2023). "Research had found that the expression of HK3 in tumor tissues may be related to T cell activation and anti-tumor immunity." (PMID 34527020, 2021). "The correlation analysis in tumor tissues showed that HK3 positively related with P65 and Snail." (PMID 33980323, 2021). "Recently, researchers have also found that HK3 expression in tumor tissues may pertain to immune status, suggesting its capability to regulate the TIME via metabolic reprogramming, similar to MCT4 and PKM2." (PMID 34269158, 2021). "We measured HK3 expression level in three paired ccRCC tumor and normal samples from FUSCC cohort." (PMID 34239350, 2021). "Higher HK3 or PKM2 expression was also accompanied by a higher tumor grade." (PMID 34269158, 2021). "Therefore, tumor tissues with high expression of HK3 can simultaneously maintain high expression of various immune checkpoints and high immune infiltration." (PMID 32508023, 2020). "In this study, we analyzed the co‐expression relationship between the glycolytic pathway gene and the immune checkpoint gene and found that the expression of HK3 in tumor tissues may be related to immune status." (PMID 32508023, 2020).
tumor (continued). "Here, we studied the co‐expression relationship between the glycolytic pathway gene and the immune checkpoint gene and found that the expression of HK3 in tumor tissues may be related to immune status." (PMID 32508023, 2020). "We received tumor tissue specimens from 50 patients with partial response (PR) and tumor tissue specimens from 50 patients with progressive disease (PD) before immunotherapy to test for HK3 expression values using RQ‐PCR." (PMID 32508023, 2020). "In addition, HK3 expression correlated significantly negatively with tumor purity in multiple cancer types." (PMID 32508023, 2020). "HK3 is a subtype of hexokinase involved in the first step of glucose metabolism, lactate is a direct by-product of glycolysis, which has been widely demonstrated to be directly involved in tumor progression by M2 macrophage polarization in tumor microenvironment." (PMID 38714539, 2024). "Since HK3 is a subtype of hexokinase involved in the first step of glucose metabolism, lactate is a direct by-product of glycolysis, which has been widely demonstrated to be directly involved in tumor progression by M2 macrophage polarization in tumor microenvironment." (PMID 38714539, 2024). "Furthermore, HK3 expression was significantly increasing along with the elevated tumor grade, had a higher level in the mesenchymal subtype compared with those in other subtypes of GBM and could independently predict poor outcomes of GBM patients." (PMID 37779195, 2023). "However, despite being a potential marker for regulating the tumor metabolic microenvironment and malignant progression, the relationship between the HK3 signal activation and progression and the ICT responses in ccRCC remains unclear." (PMID 34239350, 2021). "Furthermore, higher HK3 or PKM2 expression was accompanied by a higher tumor grade." (PMID 34269158, 2021). "In both datasets, HCC tissues had lower HK3 expression and higher PPT1 and ADCK3 expressions than paired adjacent non-tumor tissues." (PMID 37434985, 2023). "As indicated by the results, ADCK3, HK3, and PPT1 were notably correlated with tumor purity, immune score, stromal score, and ESTIMATE score." (PMID 37434985, 2023). "In conclusion, this study identified three novel predictive biomarkers (ADCK3, HK3, and PPT1) correlated with tumor purity for HCC by bioinformatics methods." (PMID 37434985, 2023). "In particular, we identified a specific signature of glycolysis-related genes in BRAF-like tumours, which display the overexpression of SLC2A1, SLC2A3, HK3, PFKFB3, PKM, LDHA and SLC16A3 (alias Mct4, the membrane channel regulating lactate efflux)." (PMID 37198319, 2023). "High HK3 and PPT1 expression and low ADCK3 expression resulted in high tumor purity, high immune score, high immune score, high stromal score, and high ESTIMATE score." (PMID 37434985, 2023). "The mRNA expression of these genes in TCGA-PRAD samples was determined, and in both non-paired and paired samples, HK2, HK3 and ADPGK were overexpressed, while GCK and HK1 were downregulated in tumor samples compared with normal tissues." (PMID 38082365, 2023). "HK3 may stimulate the abundance of infiltrating monocytes/macrophages presenting surface markers and regulate the key molecular subgroups of immune checkpoint molecules of exhaustive T cells, thus inducing the microenvironmental characteristics of active anti-tumor immune responses." (PMID 34239350, 2021). "HK1, HK3, and GPI are all key genes in glycolysis, which can promote the proliferation and development of tumor cells by promoting the glycolysis effect of tumor cells." (PMID 34708035, 2021). "The protein expression of CD44, HK3, KIF20A, and IDUA was higher in the tumor tissues compared to the normal tissue, and the protein expression of GALM and TGFA was lower in tumor tissues than normal, which was consistent with our results in TCGA." (PMID 33816274, 2021).
tumor (continued). "Afterward, the study explored the relationship between MCT4, HK3 and PKM2 with tumor purity in the TIMER database." (PMID 34269158, 2021). "The findings revealed the crucial role of HK3 in NSCLC and showed the potential relationship and the mechanism of interaction between HK3 and tumor immunity." (PMID 32508023, 2020). "Meanwhile, RT-qPCR assays revealed that ALDH6A1, FBP1, HAO2 and PSAT1 were markedly under-expressed in tumor tissues in exceeding 60% cases, and that TYMP, HK3, P4HA3, IL4I1, CYP26A1 and CPT1B were over-expressed in tumor tissues in exceeding 70% cases." (PMID 32737333, 2020). "Based on the data from Tumor Immune Estimation Resource (TIMER) and The Cancer Genome Atlas (TCGA), we studied the relationship between the expression of HK3 and the infiltration of NSCLC." (PMID 32508023, 2020). "Hexokinase‐3 (HK3), a crucial glycolytic enzyme in neuroblastoma, regulates the PI3K/AKT‐CXCL14 axis, which attracts and polarizes M2‐like macrophages, influencing directly the malignant characteristics of tumour cells." (PMID 41190507, 2025). "HK3 exerted oncogenic effects on RCC cell malignant behaviors and tumor growth." (PMID 37106446, 2023). "Furthermore, high HK3 and PPT1 expressions and low ADCK3 expression resulted in high tumor purity, high immune score, high stromal score, and high ESTIMATE score." (PMID 37434985, 2023). "As a result, GPR84, NCF2, HK3, LILRB2, and CCL18 significantly affected the overall survival (OS) of GBM patients (multivatiate Cox p < 0.05), of which the protein level of GPR84 and NCF2 was significantly increased in the tumor core region." (PMID 36177003, 2022). "Moreover, HK3 stimulates monocyte/macrophage infiltration and regulates the expression of immune checkpoint molecules PD1 and CTLA-4 in exhausted T cells, thereby inhibiting immune escape of tumor cells." (PMID 39014460, 2024). "Hexokinase-3 (HK3), as a member of the hexokinase family, may stimulate the presenting surface markers on monocytes/macrophages and regulate the key immune checkpoint molecules on exhaustive T cells, thus inducing anti-tumor immune responses." (PMID 36483554, 2022). "As per the results, there were positive and apparent correlations between HK3 expression and stromal score, immune score, and ESTIMATE score in both LUAD and LUSC, demonstrating that the degree of immune cell infiltration in tumor tissues with high expression of HK3 is also higher." (PMID 32508023, 2020). "We hypothesized that HK3 is downregulated in tumor cells but not in immune cells, so its expression status is consistent with that of immune cells in NSCLC tissues." (PMID 32508023, 2020). "The upregulation of HK3 was reported in CIMP-high tumours compared to non-CIMP ones." (PMID 33024640, 2020). "Using cell lines and primary cultures of GBM, we showed that inducible knockdown of HK2 altered tumor metabolism, which could not be recapitulated by HK1 or HK3 loss." (PMID 27588472, 2016). "The data showed that the expression of only four out of 38 genes (HK3, FBP1, PKLR, GCK) was significantly affected by tumor purity (p < 0.01) but none of them was significantly differentially expressed between Gly and Non-Gly subtypes." (PMID 30873387, 2019).